MOG (myelin oligodendrocyte glycoprotein)
Diseases named in the same sentence as MOG in open-access papers (continued):
Sharing a sentence is not in itself a finding about the gene and the disease.
depression (18 papers, 2017 to 2025). "The reduced FNCs in LG and MOG might cause abnormal reactivity to viewing images of emotional face, which has been adopted as an early biomarker of depression as reported in." (PMID 30108526, 2018). "Together with our results, these findings indicate that FCs between the bilateral AG and the MTG, IOG, or MOG play a crucial role in the mechanism of development and treatment response in depression." (PMID 39905829, 2025). "In youth with anxiety and depressive disorders, the Sertraline dose is associated with the HTR2A rs6313 polymorphism while in OCD, the MOG (TAAA)n allele was shown to be associated with an increase in white matter volume." (PMID 41009999, 2025). "Several genes with nominal significance levels were found to be associated with grip strength and depression, such as FNBP1, MOG, SACS, KMO, TECPR2, and MGTA5." (PMID 37159619, 2023). "Despite the primary role of MOG being associated with myelin and its interaction with the immune system, there exists a paucity of research specifically investigating the direct correlation between MOG and depression." (PMID 38235150, 2023). "Emerging evidence has shown that myelination-related transcriptional genes that are important for myelin structure (CNP, MAG, MOG) are significantly downregulated in patients with major depressive disorder (Aston, Jiang and Sokolov, 2005)." (PMID 35959443, 2022). "Our findings on univariable analysis in both AQP4‐Ab and MOG‐Ab patients are in agreement with this observation, although on multivariable analysis, depression remained a significant independent variable only within AQP4‐Ab patients." (PMID 32187851, 2020). "Notably, within the context of depression, a remarkable 69% of significantly down-regulated genes were found to be involved in myelin, specifically myelin oligodendrocyte glycoprotein (Mog) and ermin (Ermn)." (PMID 38916735, 2024). "The selective upregulation of MOG and MAL in response to Ω3D intervention, as observed in our study, is particularly noteworthy given their potential roles in the context of depression." (PMID 39492773, 2025). "The results showed that the progesterone level was negatively related to the cortical volume of the right MOG (r = −0.48, p=0.042) and the right SFG (r = −0.53, p=0.020) only in the anxiety–depression comorbidity group." (PMID 40959147, 2025). "Additionally, expression levels of KCNN4, MOG, and SNHG12 genes can influence inflammatory factors, potentially impacting grip strength and depression through their effects on the inflammatory response." (PMID 37159619, 2023). "On the other hand, in loMDD, the decreased MOG's function in myelination may lead to more widely damage of white matter in IFOF, resulted in depression in older age." (PMID 29867609, 2018). "According to our result, we conclude that the increased MOG in eoMDD may implicate much axon pruning in IFOF, possibly leading to depression in younger age." (PMID 29867609, 2018). "Additionally, within all three groups, participants' anxiety and depression scores do not correlate with the brain data from the MOG and SFG regions (all p > 0.097)." (PMID 40959147, 2025). "In addition, the expression levels of KCNN4, MOG, and SNHG12 genes can influence inflammatory factors, which may affect grip strength and depression by influencing the inflammatory response." (PMID 36520780, 2022).
relapsing-remitting MS (16 papers, 2011 to 2026). "Moreover, in patients with relapsing-remitting MS high-titer anti-MOG IgG correlated with disability (EDSS; Spearman r = 0.574; p = 0.025)." (PMID 22093619, 2011). "Collected sera from patients with active (symptomatic) relapsing-remitting MS (RRMS) demonstrated a higher signature of demethylated MOG cfDNA when compared with patients with inactive disease and healthy controls." (PMID 27381476, 2016). "Testing of human primers successfully detected ODC MOG cfDNA in sera of patients with relapsing-remitting MS (RRMS) and showed a correlation with disease activity." (PMID 27381476, 2016). "The ability of methylation-specific primers to successfully detect DeMeth MOG-DNA from OPCs suggests that this approach may be used to detect ODC-derived MOG cfDNA in patients with relapsing-remitting MS (RRMS)." (PMID 27381476, 2016). "Sera from 48 patients with NMO/NMOSD and 48 patients with relapsing-remitting multiple sclerosis (RR-MS) were tested for anti-aquaporin-4 (AQP4) and anti-MOG antibodies with a cell-based assay." (PMID 25889963, 2015). "Finally, it is important to mention that sut/sut mice were immunized with PLP to induce EAE, a model that is closely related to relapsing-remitting MS, whereas our xCT−/− mice were EAE-induced with MOG, which serves as a more chronic model." (PMID 28086920, 2017). "Finally, in the neurologic [MS, NMOSD, OND] cohort, one relapsing-remitting MS (RRMS) patient, one NMOSD patient, and two HDs were positive for MOG autoantibodies; nine NMOSD patients were positive for AQP4 autoantibodies; and two HDs were positive for MuSK autoantibodies." (PMID 30824481, 2019). "Interestingly, in the relapsing remitting MS mouse model, in which CD4+ T cells are specific for myelin oligodendrocyte glycoprotein (MOG), transfer of intestinal microbes from MS patients but not from healthy monozygotic twins increased incidence of disease due to decreased T cell IL-10 production." (PMID 33424846, 2020).
myasthenia gravis (15 papers, 2016 to 2025). Myasthenia gravis (MG) is a rare, clinically heterogeneous, autoimmune disorder of the neuromuscular junction characterized by fatigable weakness of voluntary muscles. "Of note, rozanolixizumab, a monoclonal antibody blocking the neonatal Fc receptor, which has already been approved for the treatment of myasthenia gravis (MG) and is currently being investigated in a phase-III study in MOG-EM/MOGAD, has been reported to preferentially lower IgG3 serum levels." (PMID 38609667, 2024).
CNS demyelination (12 papers, 2018 to 2025). A loss of myelin from nerve fibers in the central nervous system. "Given the high proportion of MOG-IgG-associated cases among cases of CNS demyelination in children, it is highly advisable to test children presenting with symptoms compatible with MOG-EM for that antibody." (PMID 35737110, 2022). "Isolated CSF positivity has been reported in patients with CNS demyelination associated with MOG autoantibodies and typical clinical-MRI phenotype." (PMID 34305787, 2021). "The findings suggest that MOG-IgA may be a novel diagnostic biomarker in a distinct subgroup of AQP4-/MOG-IgG double-seronegative patients with CNS demyelination." (PMID 37548987, 2023). "In this study, MOG-specific IgA was identified in a subgroup of patients who were double-seronegative for AQP4-/MOG-IgG, suggesting that MOG-IgA may be a novel diagnostic biomarker for patients with CNS demyelination." (PMID 37548987, 2023). "Among children who were tested for MOG-abs in this study, 14 (42.4%) of 33 children were positive, which is in accordance with the results of a previous study of Chinese children with relapsing anti-MOG-IgG-associated CNS demyelination." (PMID 33329345, 2020). "However, the 2024 ECTRIMS presentation describing proposed changes to MS diagnostic criteria identified recommendations for MOG IgG testing in children under the age of 12 presenting with new CNS demyelination, and in children older than 12 years of age with atypical presentations." (PMID 40581528, 2025). "Over the past few years, the role of immunoglobulin G serum antibodies to myelin oligodendrocyte glycoprotein (MOG-IgG) in patients with inflammatory CNS demyelination has been revisited." (PMID 29724224, 2018). "Instead, we propose to base the indication for MOG-IgG testing in patients with suspected CNS demyelination on the presence of specific clinical and paraclinical findings that are considered typical for MOG-EM and/or atypical for conventional MS." (PMID 29724224, 2018). "The diagnostic criteria for MOG-EM require the patient to have MRI findings compatible with CNS demyelination, not specific to MOG-EM, to be diagnosed with this entity." (PMID 34327021, 2021).
meningoencephalitis (12 papers, 2014 to 2025). Inflammation of the meninges and brain, generally secondary to an infectious cause. "The patient tested positive for serum MOG-IgG, confirming the diagnosis of MOG-IgG-related meningoencephalitis." (PMID 38665708, 2024). "While several recent works reported on autoantibody findings in Covid-19 patients, this is, to our knowledge, the first report of a mildly affected adult with CSF and MRI confirmed meningoencephalitis and serum anti-MOG antibodies that decreased over time." (PMID 34706651, 2021). "Headache, nausea, and vomiting accompanied by elevated CSF leukocytes suggest meningoencephalitis, which has recently been described in MOG-IgG syndrome, but they are rarely reported in MS." (PMID 31072329, 2019). "We report a Chinese patient with recurrent ON at disease initiation, who had a delayed diagnosis of MOG-IgG syndrome, until recurrent meningoencephalitis appeared and serum MOG-IgG was detected." (PMID 31072329, 2019). "Our findings suggest that autoimmune conditions, including MOG-IgG syndrome, should be considered in patients with meningoencephalitis." (PMID 31072329, 2019). "A large number of CD3+ and CD4+ T cells had infiltrated into the brains of MOG-induced or Aβ42-induced EAE mice, possibly causing meningoencephalitis." (PMID 24987466, 2014). "Young subjects with high titers of MOG-IgG may present with meningoencephalitis mimicking CNS infection." (PMID 31080435, 2019). "Of note, meningoencephalitis was recently reported in a MOG-IgG syndrome case." (PMID 31072329, 2019). "Meningoencephalitis may be helpful for the differential diagnosis and testing for MOG-IgG in atypical MS and NMOSD patients can be useful." (PMID 31072329, 2019). "Many manifestations of the MOG-IgG syndrome which are rarely seen in ADEM were observed in my patient, such as meningoencephalitis symptoms including fever, headache, nausea and vomiting." (PMID 31072329, 2019). "Testing for MOG-IgG in atypical MS and NMOSD patients, and patients with meningoencephalitis with a history of relapsing demyelinating symptoms is warranted." (PMID 31072329, 2019). "In recent years, an increasing number of reports have described cortical encephalitis and meningoencephalitis with positive MOG antibodies, despite the absence of demyelinating lesions." (PMID 40740785, 2025).
neurosarcoidosis (12 papers, 2020 to 2026). A sarcoidosis that involves the nervous system. "The majority of published studies evaluate the role of pRNFL and GCIPL thickness measurements in the differential diagnosis of MS and other inflammatory CNS conditions, e.g., NMOSD, MOG antibody-associated disease, SLE, neurosarcoidosis, and Behcet’s disease." (PMID 34770434, 2021). "Features like spinal central canal enhancement might indicate neurosarcoidosis or MOG." (PMID 38473365, 2024). "The most important differential diagnoses include MOG-EM/MOGAD, MS, neurosarcoidosis, paraneoplastic neurological syndromes, and infectious diseases." (PMID 37022481, 2023).
Optic neuropathy (12 papers, 2017 to 2025). "Over the last 2 decades, new antibodies associated with the presence of optic neuropathy have been discovered, including myelin oligodendrocyte glycoprotein (MOG) antibody and aquoporin 4 (AQ4) antibody." (PMID 39511714, 2024). "Additionally, we observed an unexpected significant decrease in RGC density in IgHMOGNlrx1−/− control mice compared to IgHMOG Nlrx1+/+ control mice, suggesting that in the setting of NLRX1 loss and associated immune dysregulation, anti-MOG immunoglobulins can lead to some degree of optic neuropathy." (PMID 39875919, 2025). "A similar diagnostic approach to optic neuropathy applies here, including testing for ANA, aPL, anti-ribosomal P protein, anti-Ro60/SSA, anti-La/SSB, anti-aquaporin 4 (AQP4), anti-myelin oligodendrocyte glycoprotein (MOG), and ANCA." (PMID 39204149, 2024). "Taken together this data suggests a more profound optic neuropathy after a single episode of MOG-ON compared to MS-ON and a tendency to affect the visual field more than the visual acuity as a long-term outcome." (PMID 32785840, 2021). "In addition to the different antibody targets; MOG-IgG optic neuropathy may be more sensitive to treatment because it involves secondary immune processes." (PMID 28125740, 2017). "In conclusion, atypical optic neuropathy seronegative for AQP4 and MOG antibodies, combined with vitreitis, retinitis, or uveitis, should prompt serological testing for CRMP5 antibody." (PMID 37448746, 2023). "TCRMOGNlrx1−/− mice showed a significant loss of RGCs compared to TCRMOGNlrx1+/+ mice, suggesting that in the absence of NLRX1, MOG-specific T-cells can also lead to optic neuropathy independent from spinal cord pathology." (PMID 39875919, 2025).
sarcoidosis (12 papers, 2019 to 2025). Sarcoidosis is a multisystemic disorder of unknown cause characterized by the formation of immune granulomas in involved organs. "Vision loss in optic perineuritis usually spares central vision, however, concomitant optic nerve involvement, especially in cases secondary to myelin oligodendrocyte glycoprotein (MOG) antibody-associated disease (MOGAD) or sarcoidosis, almost always causes decreased visual acuity and color vision." (PMID 41404456, 2025). "This highlights a diagnostic gap in imaging-based algorithms and the importance of considering other MRI-negative etiologies that may mimic TM, such as MOG-associated disease, NMOSD, paraneoplastic syndromes, and sarcoidosis." (PMID 40909059, 2025).
vasculitis (12 papers, 2019 to 2024). "Other secondary causes of autoimmune or vasculitis myelin oligodendrocyte glycoprotein (MOG) antibody disease and other common central nervous system (CNS) infection were excluded." (PMID 34712522, 2021). "Due to atypical presentation, further investigations for differential diagnosis, a vasculitis screen, myelin oligodendrocyte glycoprotein (MOG) antibodies and serum angiotensin-converting enzyme (ACE) level investigations were done." (PMID 39703256, 2024). "According to these findings, MOG-Ab disease in its acute stage should be cautiously differentiated from CNS infection and vasculitis." (PMID 31440204, 2019). "Whether vasculitis should be regarded as a primary or secondary manifestation of MOGAD, or MOG-Ab is unrelated to vasculitis diagnosis, is difficult to determine given rarity of the association." (PMID 33013639, 2020). "This case emphasized the importance of evaluating the MOG antibody in a patient with recurrent OPN, complicated with vasculitis." (PMID 35747030, 2022). "When clinicians encounter a patient with ON complicated with vasculitis, serum anti-AQP4 antibodies, and anti-MOG antibodies should be assessed, which might help obtain an accurate diagnosis." (PMID 33847609, 2021).
viral infection (12 papers, 2011 to 2024). "The FMDV titer and antigen yield were measured according to the Asia1/MOG/05-R concentration and virus infection time to determine the optimal conditions for antigen production using Asia1/MOG/05-R." (PMID 38400168, 2024). "The presence of these cells in MOG:GP mice shows that a population of clonally expanded, IgG-expressing ASCs cells persist in the brain 7 weeks following i.c. viral infection despite persistent neo-self antigen expression." (PMID 36695896, 2023). "Furthermore, our data indicate that myelin oligodendrocyte glycoprotein-immunoglobulin A and particularly myelin oligodendrocyte glycoprotein-immunoglobulin M antibodies are a rather unspecific sequel of viral infections." (PMID 38576796, 2024). "Lastly, we leveraged recently described transgenic mice that constitutively express the full-length LCMV GP under the control of the myelin oligodendrocyte glycoprotein (MOG) promoter, termed MOG:GP, to create a condition in which viral infection induces chronic autoimmune disease." (PMID 36695896, 2023). "Notably, MOG-EM mimicked bacterial CNS infection or early-stage viral infection in one patient with predominantly granulocytic CSF pleocytosis (545–720 cells/μl during acute disease) and elevated CSF L-lactate levels." (PMID 35737110, 2022). "Furthermore, we provide first evidence how a viral infection could lead to the occurrence of MOG-IgG antibodies and hope that our study could provide important information for future studies on the role of infections in autoimmune responses to MOG." (PMID 38576796, 2024). "The presence of increased myelin oligodendrocyte glycoprotein-immunoglobulin M antibodies after severe acute respiratory syndrome coronavirus 2 infection may either be a consequence of a previous infection with other coronaviruses or arise as an unspecific sequel after viral infection." (PMID 38576796, 2024). "Thus, it is intriguing to speculate that anti-MOG antibodies in HC render the same pathogenic potential as in MS patients, but HC individuals have not encountered the pathogenetically relevant viral infection." (PMID 22093619, 2011). "In patient 18, peak WCC (720 cells/μl) exceeded the maximum WCCs (463 cells/μl and 256 cells/μl) seen in two large previous studies on adult patients and paediatric patients, respectively, with MOG-EM, but extensive screening for bacterial and viral diseases was negative." (PMID 35737110, 2022).
Sjögren’s syndrome (11 papers, 2016 to 2025). "Only one (2.3%) patient was diagnosed with atopic myelitis, autoimmune myelitis, HTLV-1-associated myelopathy, MOG antibody-associated disease, and Sjogren’s syndrome." (PMID 36552976, 2022). "This phenomenon has been recognized in specific contexts, including MOG antibody-associated disease (MOGAD), GFAP astrocytopathy, Sjögren’s syndrome, and lupus myelitis." (PMID 41451231, 2025).
syphilis (11 papers, 2021 to 2025). A contagious bacterial infection caused by the spirochete Treponema pallidum. "Except for one patient who was diagnosed with syphilis-related ON, all patients underwent tests for MOG antibodies and AQP4 antibodies using cell immunofluorescence method." (PMID 38988608, 2024). "Lastly, additional autoimmune culprits of LETM were investigated such as myelin oligodendrocyte glycoprotein (MOG) antibody, neuromyelitis optica (NMO)/AQP4 IgG ELISA, HIV, and syphilis/rapid plasma reagin (RPR)." (PMID 38962621, 2024). "The serological workup for tuberculosis, syphilis, and myelin oligodendrocyte glycoprotein (MOG) was negative." (PMID 40698091, 2025). "Erythrocyte sedimentation rate and serology for syphilis, neuromyelitis optica (NMO), and myelin oligodendrocyte glycoprotein (MOG) antibodies were all normal/negative." (PMID 39803602, 2025). "Tests for tuberculin, hepatitis markers, toxoplasma, cytomegalovirus, herpes simplex virus (HSV), varicella zoster virus (VZV), human immunodeficiency virus (HIV), syphilis, aquaporin-4 antibodies (NMO), and myelin oligodendrocyte glycoprotein antibodies (MOG) were all negative." (PMID 40241898, 2025).